IL4 (interleukin 4)
Diseases named in the same sentence as IL4 in open-access papers (continued):
Sharing a sentence is not in itself a finding about the gene and the disease.
asthma (continued). "In children with Alternaria-sensitive moderate severe asthma, there was an increased Th2 response to Alternaria stimulation and increased sensitivity to IL-4 stimulation." (PMID 20298583, 2010). "In subjects with asthma, 29.8±3.5% and 36±3.5% of the IL-4+ and IL-13+ blood T cells expressed CCR8 while only 4.3±1.0% of IFN-γ+ cells expressed CCR8 (P<0.001)." (PMID 20455898, 2010). "Frequencies of CD8+ T spontaneously producing IL-4 were significantly higher in children with asthma than in healthy controls (P < .05)." (PMID 21197090, 2010). "Studies have shown that the presence of neutrophils in asthma conjugated with increased IL-4 concentrations contribute to the severity of the disease." (PMID 19753321, 2009). "Inflammation in allergic diseases such as asthma, rhinitis, and atopic dermatitis is mediated via expression of the cytokines interleukin (IL)-4, IL-5, and IL-13 from T helper-2 (Th2) cells." (PMID 19436703, 2009). "Suplatast tosilate is a novel oral anti-asthma compound that, in vitro, selectively inhibits IL-4 and IL-5 production from allergen-stimulated human Th2 lymphocytes, but not IFN-γ production from human Th1 lymphocytes." (PMID 18315837, 2008). "The inflammatory reactions in mild intermittent asthma group were driven mainly by Th2 cytokines because of the very high level of IL-4 and moderately low level of IFN-γ." (PMID 19087256, 2008). "YM-58483 inhibited airway eosinophil infiltration, IL-4 and cysteinyl-leukotrienes content and late phase asthmatic bronchoconstriction in animal models of asthma." (PMID 18315837, 2008). "IFN-γ amplifies Th1-cytokines profile, therefore, IFN-γ is considered as the prototype cytokine of Th1 lymphocytes which cross regulates IL-4, the prototype cytokine of Th2 lymphocytes in asthma." (PMID 19087256, 2008). "Nebulized ketamine at concentrations of 12.5 or 25 mg/ml significantly lessened OVA-induced airway inflammation and the induction of iNOS, IL-4 and NO in an experimental model of asthma." (PMID 17480224, 2007). "Decreased levels of asthma-associated cytokines, and especially of the TH2 cytokine IL-4, have also been frequently reported." (PMID 18053220, 2007). "There is little controversy about the requirements for IL-4 in the induction of airway inflammation and AHR, while IL-13 direct causes AHR and mucus overproduction in asthma." (PMID 17480224, 2007). "PPARγ agonists also reduce the clinical symptoms in animal models of asthma, a disease which is also thought to be predominantly Th2 type involving IL4, IL5, and IL13." (PMID 17207275, 2007). "Administration of IL-12 at the time of a single antigen challenge abolished airway hyper-responsiveness and pulmonary eosinophilia, and promoted increased IFN-γ and decreased IL-4 and IL-5 expression, in mice sensitized for asthma with ovalbumin." (PMID 16396683, 2006). "This IL-4 induction was found to be dependent on expression of STAT6, a transcription factor strongly implicated in chronic Th2 pathologies including asthma." (PMID 17134490, 2006). "Studies with IL-4 neutralization by soluble IL-4 receptor were also showing reduced asthma symptoms and improved lung function." (PMID 17034639, 2006). "Significant correlation has been identified between high levels of interleukin (IL)-4 and IL-5 and clinical severity of asthma." (PMID 16677400, 2006). "Second, our results are in line with well established associations of SNPs in IL4(-589C>T) and IL10 with asthma and atopy." (PMID 16759385, 2006). "While emphasizing the critical role of IL-13 in asthma, this study explored the relevance of IL-4 in regulation a membrane bound mucin, MUC4." (PMID 16551361, 2006). "At this time, the molecular events that link antibody to Hsp70 to the production of IL-4 and IgE and the interaction among these factors in patients with asthma remain to be investigated." (PMID 15710045, 2005).
asthma (continued). "The presence of anti-Hsp70 associated with a high risk of asthma was also correlated with the family history of asthma and higher levels of total IgE and IL-4 in the patients." (PMID 15710045, 2005). "Further analysis showed that the presence of either anti-Hsp60 or anti-Hsp70 or both was significantly correlated with the levels of IgE and IL-4 in asthma patients (p < 0.05)." (PMID 15710045, 2005). "The increased expression of IL-4, IL-9, and IL-13 in our non-T2 children may appear paradoxical but likely reflects that children with severe asthma have elevated ILC2s even when they are non-T2 (low eosinophils)." (PMID 41601686, 2026). "The downregulation of IGHV, IGKV, and IGLV genes in non-T2 asthma patients and the significantly lower IL-4 mRNA level in the non-T2 asthma than the T2-high asthma group suggest suppression of the germinal center reactions and signaling cascades driving CSR to IgE." (PMID 41601686, 2026). "Notably, alterations in the ratios of interferon gamma (IFN‐γ) and interleukin 4 (IL‐4) signify a critical disturbance in the Th1/Th2 balance, which is essential in the progression of allergic syndromes such as asthma and allergic rhinitis." (PMID 41523289, 2026). "In particular, exploring ALARM expression and function in type II immune conditions such as allergic disease, asthma, or other IL-4- and IL-13-driven pathologies will be important to determine whether this module also contributes to Th2-skewed inflammation." (PMID 41531734, 2026). "Dupilumab, a monoclonal antibody targeting IL-4 and IL-13 signaling via IL-4Rα inhibition, has emerged as an effective treatment for CRSwNP and asthma, offering significant reductions in nasal polyp burden, improvements in quality of life, and better asthma control." (PMID 41488423, 2026). "Dysregulated Th2 inflammation contributes to the primary pathological mechanism in asthma, driven by Th2 cells that secrete Th2 cytokines (interleukin (IL)-4, IL-5, and IL-13), thereby instigating specific inflammatory cascades and perpetuating an inflammatory response." (PMID 40343297, 2025). "Major cytokines involved in asthma include IL4, IL5, and IL13 derived from CD4+ T cells type II." (PMID 40468357, 2025). "Therefore, we neutralized IL-4 the main asthma-promoting T cell-derived cytokine by injecting three doses of an anti-IL-4 antibody (aIL-4), each time one hour before the intranasal OVA challenge was performed (days 28–30)." (PMID 40095032, 2025). "Hence, it has been shown that IL-4 is capable of downregulating bronchial epithelial pIgR expression in asthma." (PMID 41155294, 2025). "By targeting specific mediators of this inflammation, such as IgE, IL-5, IL-4, and IL-13, biologics aim to reduce severe asthma exacerbations, improve symptom control, and potentially reduce the need for systemic corticosteroids, thus mitigating their associated risks." (PMID 40486460, 2025). "It plays a role in the IL-4 and IL-13 signaling pathways in asthma and allergies." (PMID 40375219, 2025). "Increased IL-4, IL-5, IL-13, and IgE production characterize asthma T2 inflammation." (PMID 40486460, 2025). "In severe asthma, type 2 innate lymphoid cells, which are pivotal in the production of IL4, IL5, and IL13, as well as in T lymphocyte regulation, are markedly increased, along with macrophages, neutrophils, Th1, and Th17 cells, contributing to disease progression." (PMID 40598285, 2025). "By promoting eosinophil activity, this pathway increases the production of inflammatory cytokines, such as interleukin-4 (IL-4) and interleukin-5 (IL-5), in conditions such as asthma and chronic rhinosinusitis with nasal polyps (CRSwNP), contributing to chronic inflammation." (PMID 39940325, 2025).
asthma (continued). "In asthma, this relationship reflects converging type 2 pathways within the bronchial mucosa, driven by allergens and other environmental stimuli: local IL-4/IL-13 production induces iNOS and FeNO release, while IL-5 regulates eosinophil recruitment, maturation, and survival." (PMID 40981077, 2025). "IL-4 blockade can suppress the secretion of Th2 cytokines in a mouse model of asthma." (PMID 40005151, 2025). "Given that asthma is a widespread noninfectious chronic condition marked by type II inflammation, we assessed the levels of Th2-associated cytokines (IL-4, IL-5, and IL-13) in bronchoalveolar lavage (BAL) fluid and serum IgE concentrations." (PMID 41146240, 2025). "IL-13 and IL-4 are involved in mucus overproduction in asthma." (PMID 41303221, 2025). "Our understanding of the complex patterns of inflammation underlying asthma pathogenesis has informed the development of antibody-based biological therapies that target the T2 cytokines, IL-4, IL-5, and IL-13, in adults and in adolescents and children with refractory asthma." (PMID 41440490, 2025). "Biologic therapies targeting the IL-4/IL-13 pathway, such as anti-IL-4Rα monoclonal antibodies (mAbs), have shown improvements in lung function and reductions in exacerbation rates for severe asthma." (PMID 40370530, 2025). "M2 Macrophages dominate in Th2-high asthma, driven by IL-4 and IL-13." (PMID 41394843, 2025). "Suppressing or upregulating a single molecular route is unlikely to affect asthma because it is caused by a multitude of variables, as demonstrated for IL-4, IL5, and IL-13." (PMID 39981184, 2025). "While Th2-high asthma is driven by cytokines like IL-4, IL-5, and IL-13 and often responds well to corticosteroids and biologics, the pathogenesis and treatment of Th2-low, neutrophilic, or pauci-granulocytic asthma remain less defined and often exhibit steroid resistance." (PMID 41394843, 2025). "The identification of IL-4 as a target in asthma stems from murine studies showing that the absence of the blockade of IL-4 prevents the development of airway inflammation and other asthma features." (PMID 41145900, 2025). "IL-4 and IL-13 are key upstream mediators of type 2 inflammation in asthma, and dupilumab, by blocking these cytokines, has been shown to significantly reduce the rate of severe exacerbations and rapidly improve asthma control." (PMID 41393760, 2025). "Additionally, one patient is currently receiving dual therapy with anti-IgE and anti-IL-4 to optimize control of both asthma and nasal polyposis." (PMID 40429838, 2025). "Epithelial barrier defects have been demonstrated in asthma, AD and chronic rhinosinusitis for genetic reasons, epithelial barrier toxic substances and immune system cells and cytokines involved in the type 2 response, mainly IL-4 and IL-13." (PMID 39962262, 2025). "Furthermore, unlike P. fusca, P. ficariae triggered a greater increase in the IL-4 levels in the chronic than acute asthma model." (PMID 40558541, 2025). "Similarly, in Baghdad, IL‐4 and IL‐8 in asthma patients were considerably greater after the dust storm (p < 0.0001), but not in the control group (IL‐4: p = 0.575; IL‐8: p = 0.117)." (PMID 41185941, 2025). "The mechanism of Type 2 inflammatory asthma: Upon allergen exposure in the airways, dendritic cells (DCs) present processed allergens to Th2 lymphocytes, which subsequently secrete interleukin‐5 (IL‐5), IL‐4, and IL‐13." (PMID 41310922, 2025). "These primed DCs induce polarization of type-2 T helper cells (Th2) at regional lymph nodes, and the Th2 cytokines IL-4, IL-5, and IL-13 subsequently promote asthma symptoms by inducing inflammatory cell recruitment, IgE production, excess mucus secretion, and airway smooth muscle cell contraction." (PMID 40517435, 2025).
asthma (continued). "Furthermore, Pitrakinra, a competitive antagonist against the IL-4/IL-13 receptor, mainly treats asthma and allergic diseases by competitively binding the IL-12 receptor, mitigating the effects of IL-4 and IL-13, and easing airway inflammation." (PMID 40243848, 2025). "However, the levels of type-2 cytokines, such as IL-4 (10–25 pg/ml), IL-5 (10–16 pg/ml), and IL-13 (30–70 pg/ml), were enhanced in response to the type-2 high model compared to the type-2 low asthma model (0.5–3 pg/ml, 1–4 pg/ml, and 2–8 pg/ml, respectively)." (PMID 40512736, 2025). "Indeed, PF-07275315, a trispecific antibody targeting TSLP, IL-4 and IL-13 simultaneously, is being evaluated in Phase II trials for asthma and atopic dermatitis." (PMID 41294800, 2025). "The Th2-type cytokines IL-4 and IL-13 play key roles in asthma-related epithelial changes." (PMID 41303221, 2025). "One patient switched from anti-IL-4 to anti-IL-5 due to uncontrolled asthma." (PMID 40429838, 2025). "In asthma (particularly T2-high severe asthma), eosinophils are actively recruited to airway tissues in response to chemokines upregulated by IL-4 and IL-13 such as eotaxin-1 (CCL11), eotaxin-2 (CCL24), and eotaxin-3 (CCL26), which binds to CCR3 receptors on eosinophils." (PMID 40004192, 2025). "Studies have demonstrated that inflammatory characteristics of asthma may be related to the release of Th2 cytokines (IL-4, IL-5, IL-13 and IL-33) mediated by the regulation of arachidonic acid metabolic pathway." (PMID 40771395, 2025). "However, reasons for elevated IL‐4 and IL‐8 levels in asthma patients in a particular region like Al‐Anbar province would require further investigation." (PMID 41185941, 2025). "The most correlated targets of the FEO‐03 network on asthma were IL‐13, IL‐4, and IL‐5." (PMID 40777200, 2025). "Current research substantiates that children with acute asthma had significantly higher seropositivity for anti- M. pneumoniae IgM antibodies than children with stable asthma and asthmatic children with M. pneumoniae-positive exhibit elevated serum levels of both IL-4 and IFN-γ." (PMID 41035881, 2025). "Despite the central role of Th2 cells in producing type 2 cytokines, the field has kept a keen interest in identifying other sources of IL‐4, IL‐5, IL‐9, and IL‐13, which may also be relevant for asthma pathobiology." (PMID 40016948, 2025). "We observed that only butyrate supplementation significantly alleviated asthma severity, characterized by reduced cell counts (total cells and eosinophils) and type 2 cytokines (IL-4, IL-13, and IL-5) in BALF, as well as total and OVA-specific IgG1/IgE levels in serum." (PMID 40473603, 2025). "Furthermore, the total serum IgE levels and IL-4 concentrations were significantly higher in the PAH-exposed asthma group than those in the asthma group." (PMID 41150507, 2025). "If IL‐4 and IL‐8 levels are found to be elevated in asthma groups compared to healthy controls in Al‐Anbar province or elsewhere, it suggests a dysregulation of the immune response, potentially contributing to the development and exacerbation of asthma in those individuals." (PMID 41185941, 2025). "T2-high asthma is characterized by elevated eosinophil levels in peripheral blood and sputum; activation of Th-2 lymphocytes and innate lymphocytes (ILCs); and the release of proinflammatory cytokines such as interleukin (IL)-4, IL-5, and IL-13." (PMID 40806756, 2025). "Furthermore, levels of OVA‐specific IgE and Th2‐associated cytokines (IL‐4, IL‐5, IL‐13) in BALF were significantly reduced in the sLNP‐OVA/Cel treated group compared to other asthma treatment groups." (PMID 39921498, 2025). "The genotypic distribution of the rs2070874 polymorphism of the IL-4 gene revealed a non-significant association with childhood asthma among the study participants." (PMID 38699097, 2024).
asthma (continued). "Additionally, the expression of Il4 and neutrophilic inflammatory cytokines including Tgfb, Tnfa, Cxcl15, Elane, and Mmp9 in asthma exacerbation mice were markedly lower in LysMCreCul5fl/fl mice than in Cul5fl/fl mice." (PMID 38177117, 2024). "Indeed, STAT6 is known to participate in IL-4 signaling and its role in asthma has been extensively studied since both doctor-diagnosed asthma and blood eosinophil counts are known to be linked to STAT6 signaling and the IL-1 receptor family." (PMID 38773393, 2024). "Cytokines produced by NK2 cells, including IL-4 and IL-13, could potentially exacerbate asthma by supporting Th2 responses and inhibiting IFN responses, which may increase the likelihood of asthma worsening triggered by viral infections." (PMID 38216935, 2024). "There is a possibility that IL-4R or TSLPR is induced or increased in eosinophils from patients with severe asthma or atopic dermatitis, and these eosinophils may respond to IL-4, IL-13, or TSLP at concentrations up to 10 nM." (PMID 39624446, 2024). "IL-4 has been identified as one of the participating interleukins in the severity of asthma." (PMID 38660682, 2024). "The co-occurrence of active tuberculosis (TB) in patients with moderate to severe asthma presents unique therapeutic challenges, particularly with the advent of biologics like dupilumab, which targets the interleukin-4 (IL-4) and interleukin-13 (IL-13) pathways in asthma treatment." (PMID 39280557, 2024). "These include inflammatory cytokines IL4 (z = 0.096, p = 7.25 × 10−10) and TGFβ1 (z = −1.711, p = 5.47 × 10−8), both of which are known to play key roles in asthma." (PMID 38806494, 2024). "Furthermore, epidemiological studies have shown a strong statistical correlation between the risk of ASD and either maternal or infantile allergic/atopic disorders, including asthma, eczema, and food allergies which are often accompanied by elevated IL-4." (PMID 38315435, 2024). "Similarly, in asthma, viral infections trigger robust immune responses characterized by eosinophilic inflammation and the production of Th2 cytokines, including IL-4, IL-5, and IL-13." (PMID 39458339, 2024). "Notably, IL-4, IL-13, and eotaxin play a significant role in the eosinophilia characteristic of asthma." (PMID 38668459, 2024). "Moreover, the level of Th2 cytokines (IL‐4 and IL‐5) in the mice with acute asthma exacerbation increased more obviously which was blocked by GW administration." (PMID 38938285, 2024). "Indeed, the expression of periostin is increased in the airways of asthma patients and can be induced by IL-13/IL-4 in vitro." (PMID 38785953, 2024). "Biologic therapies targeting key inflammatory pathways involved in viral-induced exacerbations, such as interleukin (IL)-4, IL-5, and IL-13 in asthma, and tumor necrosis factor-alpha (TNF-α) and IL-1 in COPD, show potential for modulating airway inflammation and reducing respiratory symptoms." (PMID 39458339, 2024). "Dupilumab is a humanized monoclonal antibody targeting interleukin-4 and interleukin-13 cytokines currently indicated for moderate-to-severe atopic dermatitis, severe asthma, chronic rhinosinusitis with nasal polyposis, and moderate-to-severe prurigo nodularis." (PMID 39185064, 2024). "Regarding the diagnosis of MP asthma, the joint detection of 25-(OH)-D, IL-4, IFN-γ, and IFN-γ/IL-4 may improve diagnostic capabilities of MP infection-related asthma." (PMID 39572779, 2024). "eCOPD patients could be distinguished from the severe asthma group by enhanced IL-4 levels and reduced serum levels of eotaxin-1 and sFcεRI (p < 0.05)." (PMID 39766355, 2024). "Other investigations have required the coadministration of αGalCer to induce allergic asthma, failing to induce the disease only by the administration of OVA or ragweed, suggesting that NKT cells, antigen-specific TH2 cells, and IL-4 were needed for the development of asthma, respectively." (PMID 38629075, 2024).